IL1B (interleukin 1 beta)
Diseases named in the same sentence as IL1B in open-access papers (continued):
Sharing a sentence is not in itself a finding about the gene and the disease.
COVID-19 (continued). "A study conducted in ICU and non-ICU COVID-19 patients in Wuhan, China, reported elevated levels of IL-1β, IL-7, IL-8, IL-9, IL-10, FGF, G-CSF, GM-CSF, IFN-γ, IP-10, MCP-1, MIP-1α, MIP-1β, PDGF, TNF-α and VEGF in patients compared to healthy controls." (PMID 34603318, 2021). "In contrast to the severe COVID-19 group, the critical COVID-19 group was notable for the existence of more and different correlations between proinflammatory cytokines: TNF-α, IL-1β and cells, including lymphocyte subpopulations: T lymphocytes CD8+, B lymphocytes and Treg cells." (PMID 34064802, 2021). "Recent published studies in adult populations have reported that elevated levels of inflammatory cytokines levels such as TNF-α, IL-1β, IL-6, IL-10, IL-17, IL-18, IFN-γ are seen in active COVID-19 individuals compared to seropositive individuals and healthy controls." (PMID 33813138, 2021). "Notably, the levels proinflammatory cytokines such as IL-1β, IL-17A, IL-2, and RANTES remained elevated in COVID-19 patients at the early convalescent phase, particularly in those with prior cardiovascular risk, compared to healthy controls." (PMID 33752798, 2021). "The hyper inflammation and cytokine storm, common in COVID-19 patients, with an elevation in IFN-γ, IL-1β, IL-6, IL-17, and TNF, promotes muscular proteolysis, decreased protein synthesis, and satellite cells dysfunction, possibly another mechanism of muscle wasting in these individuals." (PMID 33613573, 2021). "Clinically, targeting IL-1β, IL-6, and TNF-α have gained some success in severe COVID-19 patients." (PMID 34150848, 2021). "In this study, 44 potential targets were obtained through the intersection of the disease targets of COVID-19 and the action targets of AE, which are mainly related to inflammatory or immune factors, such as IL-6, MAPK1, MAPK8, IL1B, RELA, CXCL-8, CCL2, and PTGS2." (PMID 33658066, 2021). "Zn supplementation may be able to reduce inflammatory cytokines (IL-6 and IL-1β), enhancing the protective type-I IFN response in COVID-19." (PMID 33921297, 2021). "MIS-A patient PBMC responses to SARS-CoV-2 were largely similar to those of PBMCs from ICU patients with severe COVID-19, however IFNγ, TNFα; and IL-1β responses tended to be higher in MIS-A PBMCs although not significantly across all cases." (PMID 34531865, 2021). "Cytokine storm, hyperinflammation, multiorgan failure, and acute respiratory distress syndrome were described in COVID-19 patients with high fever, dyspnea, lymphopenia, and high serum ferritin, D-dimers, C-reactive protein (CRP), and cytokines, including IL-1b, IL-6, and TNF-α." (PMID 34578460, 2021). "The identified crucial cytokine panel, including IL6, IL1β, IL10, CXCL10, IGF1, and GALECTIN-1, may offer the selective targets to improve the efficacy of COVID-19 therapy." (PMID 34238338, 2021). "Indeed, activation of CASP1 by activating inflammasomes in response to the SARS-CoV-2 infection activates IL1B and IL18 and contributes to hypercytokinemia in COVID-19 patients." (PMID 34975885, 2021). "By contrast, the dynamic of MIP-1β, IL-1β, MIP-1α and IFN-γ showed a different evolution pattern, with a significant increase at month 1 and/or 3 among patients with mild/moderate disease, compared to those with severe COVID-19." (PMID 34835384, 2021). "Although some COVID-19 cases have very high serum concentration of IL-17, IL-1β and TNF-α, the average levels of these cytokines did not change dramatically compared to normal values." (PMID 33995382, 2021). "Furthermore, the downstream factors of TLR7 and BTK in TLR pathway, such as MYD88, IRF7, NFKB1, and JUN, and cytokines (TNF, IL1B, and IL18) were elevated in men with severe COVID-19." (PMID 34330889, 2021). "Moreover, IL-1β and TNF-α promote the response of Th17, by producing IL-17, although their role in COVID-19 immunopathogenesis is still to be clarified." (PMID 33669218, 2021).
COVID-19 (continued). "Whilst the levels of some cytokines (i.e., IL-6, IL-8, IP-10, TNF-α, sCD25) declined one month after the SARS-CoV-2 diagnosis, others (MIP-1β, IL-1β, MIP-1α and IFN-γ) showed higher levels at month 1 and/or 3 in patients with mild/moderate disease compared to those with severe COVID-19." (PMID 34835384, 2021). "In monocytes from severely affected COVID-19, IFN-1 response, and TNF/IL-1β-driven inflammation co-existed and were absent in patients with milder COVID-19." (PMID 34940755, 2021). "While CXCL9, CXCL10 and CXCL11 expression levels were increased both in moderate and severe disease compared to healthy levels, IL1β, IL6, TNF as well as CCL2, CCL3, CCL4 and CCL7 were expressed at higher levels in lung macrophages from patients with severe COVID-19." (PMID 34367190, 2021). "We found that severe COVID-19 patients displayed, as extensively already reported, high level of circulating inflammatory cytokines, including IL-6, TNF-α, IL-1β and chemokines such as CXCL-10, CCL-2 and CXCL-8 contributing to the diffuse inflammatory status and the so-called cytokine storm." (PMID 34473805, 2021). "Interestingly, cytokines such as IL-1β, IL-6, TNF-α, and MCP-1 appear to be elevated in COVID-19 patients and also can induce HPSE expression." (PMID 33123154, 2020). "As IL-1β signal inhibition by anakinra treatment showed a favorable outcome, BTK targeted therapy may also be a prospective therapeutic option for COVID-19." (PMID 32834892, 2020). "Several other cytokines, including IL-1β, IL-12p40, and IL-17, were not detectable in the severe COVID-19 patients." (PMID 32826331, 2020). "As expected, higher plasma levels of pro-inflammatory cytokines IL1β, IL6, IL8, and TNFα at admission and before specific treatment were positively correlated with the severity of COVID-19 symptoms (p < 0.0001 for all cytokines), confirming the results from previous studies." (PMID 33585507, 2020). "Higher levels of interleukin (IL)-1β, interferon-γ, CXCL10, monocyte chemoattractant protein-1, granulocyte colony-stimulating factor, monocyte inhibitory protein-1, and TNF-α were observed in COVID-19 patients requiring ICU admission." (PMID 32498376, 2020). "SARS-Cov2 induces the production of IL-1β which is a mediator of lung inflammation, fever, and fibrosis, following TLR stimulation and inflammasome activation, thus contributing with an “additional via” to the cytokine storm during COVID-19." (PMID 33633566, 2020). "Cytokine storm pathophysiology in CoViD-19 is often reported to be due to high levels of IL-6 in individuals, although this, we believe, could synergize with TNF-α and IL-1β levels." (PMID 32574269, 2020). "Although IL-6 is regarded as a marker of pneumonia in CoV infections, it has now become evident that abrupt release of IL-1β and TNF-α could contribute to the severity of CoViD-19 pathogenesis." (PMID 32574269, 2020). "Cytokine storm is hypercytokinemia that increases the volume of pro-inflammatory cytokines in the serum (e.g. IL-1β, IL-6, IL-12, INF-γ) and chemokines (CXCL10 and CCL2), and is correlated with pulmonary inflammation and extensive lung involvement as seen in COVID-19 patients." (PMID 33205807, 2020). "A retrospective study of 21 patients identified significant elevations of plasma IL-6, IL-10, TNFα and IL-2 receptor in severe (n = 11) compared to moderate (n = 10) cases of COVID-19, whereas IL-1β and IL-8 levels were not significantly different." (PMID 32629875, 2020). "By comparing COVID-19 and severe influenza, we report that the TNF/IL-1β-driven inflammatory response was dominant in COVID-19 across all types of cells among PBMCs, whereas the up-regulation of various interferon-stimulated genes (ISGs) was prominent in severe influenza." (PMID 32651212, 2020). "Although we observed elevated levels of IL-1β and TNFα in some COVID-19 patients, this was not consistent across the cohort." (PMID 32909002, 2020).
COVID-19 (continued). "It is presently seen in fatal cases that homeostasis of immune system is not maintained resulting in imbalance of immunological cells and cytokine levels mainly IL-1β and IFN-γ during dual mode of infection such as viral pneumonia increases the complications in COVID-19 patients." (PMID 33634060, 2020). "In our study, cytokines including IL-1β, IL-6, IL-10, and TNF-α were elevated in severe COVID-19 and active AOSD, compared with healthy controls, indicating the potential contribution of cytokine storm in pathogenesis of COVID-19 and AOSD." (PMID 33552062, 2020). "In addition, increased levels of plasma pro-inflammatory cytokines such as Interleukin (IL)-1β, IL-6, IL-8, and tumor necrosis factor-α (TNF-a) are observed in severe COVID-19 patients, indicative of a cytokine storm and subsequent ARDS development." (PMID 32695122, 2020). "Regarding the downregulated geneset, MHC II molecules, including HLA-DQA1, HLD-DRA, HLA-DRB1, HLA-DMB, HLA-DMA, etc., and cytokine/chemokine genes, including IL1B, TNF, CCL3, CCL4, and CXCL8 were expressed at lower levels in COVID-19 patients, especially those with severe diseases." (PMID 33101705, 2020). "Interestingly, it has been reported that levels of TNF-α and IL-1β, and some chemotactic cytokines (IL-8 and MCP-1) rise early in COVID-19 hypercytokinemia, facilitating a subsequent sustained increase in IL-6." (PMID 33292350, 2020). "Therefore, we propose that anti-inflammatory strategies targeting not only inflammatory cytokines, including TNF, IL-1β, and IL-6, but also pathological IFN-I response needs to be investigated for the treatment of patients with severe COVID-19." (PMID 32651212, 2020). "Notably, cytokine and chemokine profiles linked to the viral response are consistent with those upregulated in lung autopsy samples from COVID-19 patients compared to control donors, including CXCL5, CXCL6, CXCL10, and IL-1β." (PMID 33162939, 2020). "In our study, we first showed that despite similar respiratory severity, plasma concentrations of numerous cytokines characterizing the “cytokine storm” (i.e. IL-1β, IL-6, IL-8, IL-15, TNF-α, CCL2, CCL4, CCL19, CCL20, TGF-α) were lower in COVID-19 compared to non-COVID-19 patients." (PMID 33272291, 2020). "The activation of AP-1 and NF-κB signals caused an increased expression of inflammatory factors such as TNF-α, IL-1β, IL-8, MIP-1α and MIP-1β according to the KEGG enrichment analysis, which might be detrimental to COVID-19 rehabilitation." (PMID 33361761, 2020). "The phenomenon of a cytokine storm – originally characterized in acute severe COVID-19 – refers to an excessive and uncontrolled release of pro-inflammatory cytokines, including interleukin-6 (IL-6), tumor necrosis factor-alpha (TNF-α), and interleukin-1 beta (IL-1β)." (PMID 41497070, 2026). "The expression levels of a 13-cytokine panel (IL-1α, IL-1β, IL-2, IL-4, IL-5, IL-6, IL-8, IL-10, IL-12, NF-κβ, and IFN-α, IFN-β, and IFN-γ) were measured by qRT-PCR from peripheral blood mononuclear cells (PBMC) obtained from the patient with TEN and their parents (which were positive for COVID-19)." (PMID 39941142, 2025). "Compared to non-severe adult COVID-19 patients, severe adult patients exhibited dramatically increased secretion of Th1 proinflammatory cytokines, in particular, IL-1β (40.79 vs. 207.84), IL-6 (112.90 vs. 304.15), and IL-8 (1454.66 vs. 2829.79, p = 0.001) in BALF." (PMID 39967737, 2025). "Notably, in classical monocytes, type I IFN responses were present alongside TNF and IL-1β in patients with severe COVID-19 but not in mild COVID-19 cases." (PMID 40742121, 2025). "Indeed, COVID-19 triggers a hyperinflammatory response—also known as a cytokine storm—which is marked by elevated levels of pro-inflammatory cytokines such as IL-6, TNF-α, and IL-1β." (PMID 40217761, 2025).
COVID-19 (continued). "The results showed that IL-1β, IL-2, IFN-β, IFN-γ, IL-17, GM-CSF, and TFN-α had a slightly higher correlation with metabolic phenotype 2 in non-survivors, indicating a potential association with COVID-19 mortality outcome." (PMID 41002992, 2025). "As a group (although not individually as this is not a longitudinal study), there was a moderate negative correlation with IL-1β in people who recovered from COVID-19 (r = −0.46, p = 0.005), while in people with lingering neurological sequelae, IL-1β did not decrease over time (r = 0.12, p = 0.395)." (PMID 41369364, 2025). "Studies have established that increased levels of IL-1β, IL-2, IL-6, IL-10, IFN-γ, TNF, IFN-γ-inducible protein 10 (IP-10), granulocyte macrophage-colony stimulating factor (GM-CSF), and monocyte chemoattractant protein-1 (MCP-1) correlate with COVID-19 severity." (PMID 39940907, 2025). "Moreover, the SARS-CoV-2 S protein can only prime inflammasome formation and release of mature IL-1β in macrophages derived from patients with COVID-19 but not in macrophages from healthy SARS-CoV-2 naive individuals." (PMID 38133713, 2024). "Considering the pronounced inflammatory response in COVID-19 and CDI infections, with elevated levels of IL-6, TNF-α, IL-1β, and IP-10, as well as the reported dysbiosis, FMT could play a crucial role in the treatment of CDI or more severe conditions like COVID-19 and C. difficile co-infections." (PMID 39432486, 2024). "For this, we have measured the expression of the different players implicated in the NLRP3 inflammasome pathway including NLRP3, CASP-1, ASC, IL-1β and IL-18 in whole blood of severe COVID-19 patients treated or not with 50,000 IU cholecalciferol once per week for 2–3 weeks during their stay at ICU." (PMID 38748756, 2024). "Finally, we demonstrate that two pro inflammatory cytokines produced by inflammasome activation, IL-18 and IL-1β, do not restrict viral replication and are potential targets to ameliorate pathological inflammation in severe COVID-19." (PMID 39240187, 2024). "The study identified IL-6, TNF, IL-1β, IL-10, and IL-2 as the five most distinctive cytokines that could effectively differentiate between individuals who had COVID-19 (including those with long COVID) and those who had never been exposed to the virus." (PMID 39518964, 2024). "Although the role of the exacerbated inflammatory response in developing clinical complications in patients with COVID-19 has been recognized from the beginning, and therapies directed against inflammatory mediators such as IL-1β and IL-6 have been proposed, the results have not yet been conclusive." (PMID 39637135, 2024). "It is well established that viral infections such as COVID-19 are characterised by increases in pro-inflammatory cytokines such as IL-6, TNF-α, IL-12p40, and IL-23, while influenza and HIV-1 infections are characterised by increased production of IL-1β, IL-6, and TNF-α." (PMID 39123583, 2024). "Further studies will be necessary to determine whether COVID-19 patients carrying the 5G5G, but not 4G4G genotype, or patients with other IL-1β-related inflammatory diseases might benefit from drugs blocking IL-1 signaling." (PMID 39281671, 2024). "Similarly, mRNA levels of NF-κB target genes, including IL1β and IL10, were significantly increased independently of the severity of COVID-19, and CXCL1 and cyclooxygenase 2 (COX2) mRNA expression was significantly higher in PBMCs from patients with severe and critical COVID-19." (PMID 37310504, 2023). "Therefore, our data indicated that genes such as Il1b, S100a, Il1rn and other inflammatory factors which were highly expressed by CD14+ monocytes, may be the main contributors to the cytokine storm in COVID-19." (PMID 36817436, 2023).
COVID-19 (continued). "This study aimed to address the level of three cytokines which were interleukin-1-beta (IL-1β), interleukin-6 (IL-6), and tumour necrosis factor-alpha (TNF-α), with different blood parameters to the formation of cytokine storm or any complication among COVID-19 patients." (PMID 37363608, 2023). "Studies have shown that patients critically ill with COVID-19 have higher serum concentrations of proinflammatory cytokines and chemokines, including granulocyte colony-stimulating factor, monocyte chemoattractant protein-1, TNF-α, IL-6 and IL-1β, than healthy individuals." (PMID 36979888, 2023). "Both GA/18β doses modulated inflammatory response by reducing mainly IL-17A expression, which in turn kept IL-1β, IL-6, IL-8 and TNF-α interleukins unchanged, indicating significant modulation of key interleukin levels to prevent exacerbation of the immune response in COVID-19 patients." (PMID 38283346, 2023). "In this group, we consistently observed strong correlations of IL-5 with IFN-γ and IL-1β with TNF-α, supporting the hypothesis of synergistic Th1 and Th2 responses and cooperative activity between type 1 and type 2 macrophages in controlling COVID-19." (PMID 37047752, 2023). "The serum concentration of TNF-α and IL-1β levels did not change among COVID-19 patients." (PMID 37363608, 2023). "The absence of significant changes in NLRP3 expression and IL-1β levels might reflect the complexity of the immune response in COVID-19." (PMID 37723427, 2023). "It was shown that targets of the drug combinations (including TNF, IL1B, IL10, and CCL2) (p=5.72×10−5) and, specifically, its individual drugs including EH (p = 0.00142), PR (p=4.37×10−4), and GR (p=5.81×10−5) are significantly overlapped with COVID-19-related genes obtained from the CTD database." (PMID 36611603, 2023). "However, the lack of significant change in NLRP3 expression and serum IL-1β levels between COVID-19 cases and HS is intriguing." (PMID 37723427, 2023). "In one study, in patients with COVID-19-associated thrombotic events, no statistical significance was recorded between serum levels of inflammatory markers (CRP, ferritin), age, and other clinical characteristics, except for IL-1β and soluble P-selectin." (PMID 36979908, 2023). "However, the presence of inflammasome-related proteins (ASC, IL-1β, IL-18, gasdermin D) in the plasma of severe COVID-19 patients is not always correlated with unfavorable outcomes." (PMID 37508374, 2023). "Very recently, a cohort study showed that acute COVID-19 or postacute sequelae of COVID-19 (PASC) are not related to autoantibodies but to elevated plasma levels of proinflammatory cytokines such as interleukin-1 beta (IL-1β), IL-6, and tumor necrosis factor alpha (TNF-α)." (PMID 37095536, 2023). "However, three other studies have shown that increased IL-1β levels in PBMCs, serum, or plasma did not correlate with COVID-19 severity." (PMID 37799713, 2023). "Increased plasma levels of IL-1β, IL-6, and IL-8 in patients with COVID-19 also has a negative effect on the RBCs’ ultrastructure and induces signs of eryptosis, a form of suicidal death of RBCs, that exhibits an increased tendency of adhering to ECs as well as platelets, contributing to thrombosis." (PMID 36979908, 2023). "Indeed, a cytokine storm had been observed in severely ill COVID-19 patients, and most of these patients exhibited markedly increased serum levels of proinflammatory cytokines, such as interleukin (IL)-6, tumor necrosis factor alpha (TNF-α), GM-CSF, and IL-1β." (PMID 37762435, 2023). "Also, the interleukins (IL1B, IL15, IL16, and IL32) were found to be upregulated in the active COVID-19 patients, indicating a T cell and monocyte-mediated proinflammatory response during active COVID-19." (PMID 36532041, 2022).